AR (androgen receptor)
Diseases named in the same sentence as AR in open-access papers (continued):
Sharing a sentence is not in itself a finding about the gene and the disease.
breast carcinoma (continued). "Modulating AR activity either with an AR agonist or AR antagonist with other treatments has been tested in numerous clinical trials for breast cancer patients." (PMID 38339092, 2024). "Similar to other hormone receptors in breast cancer, we describe a discrepancy between the AR status of DTCs and the corresponding PT." (PMID 37902839, 2024). "AR is a type I nuclear receptor that regulates gene transcription for cell differentiation, proliferation, apoptosis, or angiogenesis of breast cancer." (PMID 38215156, 2024). "The AR gene plays a role in the transformation of male breast epithelial cells into neoplasms, expressed in up to 74% of male breast cancer cases." (PMID 39314558, 2024). "Conversely, in cancer cells, KHDRBS1 acts as an oncogene, promoting breast cancer metastasis by upregulating EPHA3 gene, and regulating the expression of the androgen receptor splice variant AR-V7 to promote prostate cancer growth." (PMID 38660302, 2024). "In conclusion, we have revealed a novel interaction between AR and GATA3 transcription factors in breast cancer cells that was functionally linked to promotion of a more differentiated phenotype." (PMID 38317241, 2024). "There is evidence of cross-talk between the AR and ERα to facilitate the growth of some breast cancers." (PMID 38339092, 2024). "MiRNAs regulate the expression of gene drivers involved in critical signaling pathways in TNBC, such as the AR gene, and their expression varies across races and breast cancer subtypes." (PMID 39769441, 2024). "The hormone receptor statuses—estrogen receptor (ER), progesterone receptor (PR), and androgen receptor (AR)—showed statistically significant differences in distribution across breast cancer B classifications." (PMID 39456566, 2024). "The main aim of this study is to evaluate the AR expression in breast cancer and to correlate it with the Ki67 proliferative index and other clinicopathological prognostic factors." (PMID 39497884, 2024). "In ERα-positive breast cancer cell lines, estrogen stimulation leads to the nuclear translocation of AR and its binding to unique DNA sites that are enriched in estrogen response elements and that overlap with ER-binding sites." (PMID 38339092, 2024). "The combination of EPI-7170 with palbociclib was superior to monotherapy in altering the cell cycle in AR-positive breast cancer cell lines, reducing the percentage of cells in the S phase, and increasing cell cycle arrest in the G1 phase." (PMID 38339092, 2024). "On the other hand, a recent study revealed that AR interactions with c-Myc in breast cancer cells mediate the M2 polarization of macrophages." (PMID 39682229, 2024). "The expression of the AR in breast cancer cells, like that of the ER, is inversely correlated with immune cell infiltration and cytotoxic immune activity, indicating that AR signaling has an immunosuppressive effect in breast cancer." (PMID 39682229, 2024). "AR plays an inhibitory role in estrogen-dependent diseases, and in approximately 90% of ER-positive breast cancers, ar shows positive expression, correlating with better patient prognosis." (PMID 38827320, 2024). "We recently demonstrated that AR inhibits growth and acts as a tumor suppressor in normal breast tissues and ER+ breast cancers and acts on multiple cell types to induce striking changes in the female breast that are consistent with reduced cancer risk." (PMID 38317241, 2024). "Regarding ER+ breast cancer and considering the beneficial effect of AR in those cases, the use of AR agonists would benefit the treatment of this disease, in a non-resistant scenario." (PMID 39338407, 2024). "Overall, estrogen/ER signaling and androgen/AR actions in breast cancer cells tend to promote an immunosuppressive tumor microenvironment." (PMID 39682229, 2024).
breast carcinoma (continued). "In a previous study, we identified multiple AR-dependent secreted proteins produced by breast cancer cells." (PMID 38349455, 2024). "AR was identified as a hub protein that is highly expressed in breast cancer and 2-hydroxynaringenin efficacy of counter TNBC requires further investigation both in vitro and in vivo." (PMID 40860264, 2024). "In our study, positive AR expression was found in 139/192 cases (72.4%) of invasive mammary carcinomas." (PMID 39497884, 2024). "The influence of steroid hormones and AR’s role on breast cancer tumor development is a target that is currently being addressed for the improvement of current therapies." (PMID 39063165, 2024). "In breast cancer, androgens are thought to inhibit the motility of MCF-7 breast cancer epithelial cells by promoting the secretion of soluble factors via AR signaling activation in CAFs." (PMID 39682229, 2024). "Preclinical studies have demonstrated that AR inhibitors reduce the tumor growth of some AR-positive breast cancers." (PMID 38339092, 2024). "Though AR is considered an emerging prognostic marker in breast cancer, there are conflicting published data regarding the correlation between AR expression and clinicopathological prognostic parameters of breast cancer patients." (PMID 39497884, 2024). "Currently, enobosarm is being evaluated as a monotherapy in clinical trials for multiple pathologies, including ER-positive/AR-positive breast cancer as well as AR-positive TNBC breast cancer (NCT01616758, NCT02463032, and NCT04869943)." (PMID 38339092, 2024). "We have previously shown that the AR and FOXA1 cistromes demonstrate an extraordinary overlap in MDA-MB-453 cells and that FOXA1 is required for AR to regulate genes that define the molecular apocrine breast cancer phenotype." (PMID 38317241, 2024). "By using ToxPi metrics, we confirmed the previous assumption that CBD is the best cannabinoid when the simultaneous action towards aromatase, ER, and AR is considered, which highlights its therapeutic potential for ER+ breast cancer." (PMID 39338407, 2024). "To determine if KCZ functions through CYP3A4 or AR in our combination treatment studies, we evaluated target availability in normal and breast cancer cell lines." (PMID 39768178, 2024). "With more and more research on AR signaling in breast cancer, support is accumulating for the idea of AR playing an essential role in some breast cancers." (PMID 38339092, 2024). "Recently, Hickey and co-workers re-evaluated the role of the AR in breast cancer and provided compelling evidence for the use of an agonist to activate AR signalling as a therapeutic intervention in ER+ breast cancers." (PMID 39088439, 2024). "We propose that AR/GATA3-mediated induction of KDM4B facilitates maintenance of a luminal epithelial transcriptome in breast cancer cells and forms part of a tumor suppressive nexus regardless of ER status." (PMID 38317241, 2024). "Due to the critical role of GATA3 in breast development and as a regulator of ER signaling in breast cancer, we chose to further investigate its functional interaction with AR." (PMID 38317241, 2024). "The AR is expressed in all major subtypes of breast cancer but mechanistic understanding of AR as a transcription factor in is limited." (PMID 38317241, 2024). "There are a vast number of clinically approved therapeutic options that target AR, thereby facilitating a rapid translation of any of these treatments for clinical testing in breast cancer patients." (PMID 38339092, 2024). "Androgen receptor (AR) expression has demonstrated predictive value for potential response to adjuvant hormonal therapy in estrogen receptor-positive (ER+) breast cancers." (PMID 40860264, 2024). "This review focuses on the roles of ER and AR signaling in both breast cancer cells and stromal cells, summarizing recent findings regarding the effects of estrogens and androgens on stromal cells within the breast cancer microenvironment." (PMID 39682229, 2024).
breast carcinoma (continued). "We validated that KDM4B protein expression was increased by DHT in ER+ and ER- breast cancer cell lines, and this increase was abrogated by AR knockdown." (PMID 38317241, 2024). "In summary, our findings strongly suggest ZAG is a novel mediator of AR-dependent immunomodulation in the breast cancer microenvironment." (PMID 38349455, 2024). "Abiraterone increased the sensitivity of both AR-positive and AR-negative breast cancer cells to cytotoxic T lymphocyte-mediated lysis." (PMID 39598525, 2024). "Although TNBC is characterized by the lack of expression of ERα, PR and HER-2 overexpression, this breast cancer subtype is capable of expressing other receptors like the androgen receptor (AR) or the estrogen receptor β (ERβ)." (PMID 38338747, 2024). "The androgen receptor (AR) is expressed in over 70% of breast cancer cases, with positivity most prevalent in luminal subtypes, followed by TNBC." (PMID 39768978, 2024). "Phytochemicals that inhibit breast cancer target were retrieved from the PubChem database and virtual screening was performed using PyRx against the AR protein." (PMID 40860264, 2024). "The tumor cells from both sexes had similar transcript levels of estrogen receptor alpha (Esr1), androgen receptor (Ar), and human epidermal growth factor receptors (Erbb2, Erbb3), which are the attributes of the Luminal B breast cancer subtype." (PMID 39684829, 2024). "Out of the 192 breast cancer patients, 139 (72.4%) cases were AR-positive and 53 (27.6%) cases were AR-negative." (PMID 39497884, 2024). "Since transcription factors interact with numerous other nuclear proteins to regulate transcription, we performed an unbiased proteomic analysis of molecularly diverse breast cancer cell lines to characterize their AR-dependent multi-subunit protein complexes." (PMID 38317241, 2024). "To expand our analysis, we examined all breast cancer cases in the TCGA dataset, which yielded 720 cases with expression data for both AR and the same six miRNAs." (PMID 39769441, 2024). "We observed a strong positive correlation between HER3 and both ER-α and AR expression in breast cancer cell lines and breast tumours." (PMID 38228924, 2024). "AR is commonly expressed in breast cancer tissues, especially in ER-positive breast cancer, but the roles that AR plays are controversial." (PMID 38965614, 2024). "AR antagonists, such as bicalutamide and enzalutamide, or the ablation of androgen production have been investigated in clinical trials for breast cancer." (PMID 38339092, 2024). "In clinical datasets, high expression of KDM4B, but not EHF (data not shown), was associated with better patient outcomes, although EHF is one of 142 genes comprising a gene signature of AR activity that is prognostic in ER+ breast cancer." (PMID 38317241, 2024). "In the search for the development of alternative targeted therapies for breast cancer, it was discovered that the closely related androgen receptor (AR) can be detected in the majority of all types of breast cancers." (PMID 38339092, 2024). "In ER+ breast cancer cases, AR antagonizes ERα signaling, contributing to the decrease in cell proliferation and tumor growth." (PMID 39338407, 2024). "The hormone-independent AR pathway has mainly been studied in prostate and breast cancers but much less in glioblastoma." (PMID 38233838, 2024). "We summarize recent findings focusing on the effects of ER/AR signaling in breast cancer cells on stromal cells, as well as the direct effects of ER/AR signaling in stromal cells." (PMID 39682229, 2024). "This study aimed to assess the role of ZAG protein in the AR-dependent immune-regulatory mechanisms in the breast cancer microenvironment." (PMID 38349455, 2024). "In this case, the activation of AR, rather than its inhibition, would be the more suitable treatment option for patients with ERα-positive breast cancer when AR behaves as a tumor suppressor." (PMID 38339092, 2024).
breast carcinoma (continued). "Truncated AR proteins were reported in different diseases such as breast cancer, androgen insensitivity syndrome, and complete testicular feminization in the 1990s." (PMID 38339092, 2024). "A previous study found that ZDHHC21 is required for endogenous androgen receptor palmitoylation, membrane localization, and signal transduction in breast cancer cells." (PMID 38195819, 2024). "This knowledge is critical for development of rational therapeutic strategies to target AR in breast cancer." (PMID 38317241, 2024). "Three prior meta-analytical studies have demonstrated a prolonged DFS in breast cancer patients with AR positivity compared to those with AR negativity." (PMID 38555429, 2024). "To address KCZ dependency on AR in our models, we knocked down AR in MDA-MB-231 breast cancer cells using siRNA." (PMID 39768178, 2024). "In ERα-positive breast cancer, higher levels of nuclear AR protein are usually correlated with improved outcomes and better survival regardless of treatments." (PMID 38339092, 2024). "A previous study has shown that ZDHHC21 mediates endogenous androgen receptor palmitoylation and enhances membrane trafficking in breast cancer cells." (PMID 38195819, 2024). "The majority of combination studies with an AR antagonist tested in clinical trials for breast cancer have been with the antiandrogen enzalutamide." (PMID 38339092, 2024). "Since only 36.8% of triple negative breast carcinomas showed AR positivity in this study and the overall specificity of AR for breast cancer was low, the use of AR IHC for verifying breast cancer origin of AR positive metastases is limited." (PMID 38790919, 2024). "AR has been extensively investigated in “classic” hormone-dependent cancers such as prostate and breast cancer." (PMID 38790919, 2024). "Recently, we and other researchers found that AR expression is inversely correlated with immune cell infiltration in breast cancer tissues." (PMID 38349455, 2024). "AR is ubiquitously expressed in 72–79% of primary breast cancers, although its expression differs by breast cancer subtype, and is more frequently expressed in hormone receptor positive breast cancer compared to hormone receptor negative breast cancer." (PMID 37345085, 2023). "On the other hand, there is evidence that androgen receptor activity positively regulates the generation of cancer stem cells in other types of neoplasia, such as breast cancer or glioblastoma." (PMID 37894767, 2023). "Our study found that AR was widely highly expressed in HR + breast cancers, and the expression rates in HR + /HR- and HR + /HR- were 82.5% and 85.9%, respectively, while the expression rate in TNBC was only 34.6%." (PMID 37099044, 2023). "AR-positive patients had a good prognosis after neoadjuvant therapy in HR-positive breast cancer, but a poor prognosis in HR-negative breast cancer." (PMID 37099044, 2023). "We used a technique called immunohistochemistry to study AR expression in BrM from 57 breast cancer patients." (PMID 37345085, 2023). "AR expression was associated with the outcome of HR + /HER2- and HR + /HER2 + breast cancer and TNBC." (PMID 37099044, 2023). "Growing evidence has indicated that the androgen receptor modulates breast cancer progression (Magklara, Brown & Diamandis, 2002)." (PMID 37842046, 2023). "The unaromatizable androgen Dihydrotestosterone (DHT) and the synthetic agonist of AR Mibolerone (Mb) inhibit cell proliferation and trigger apoptosis in ER+ breast cancer cells by activating AR." (PMID 37686282, 2023). "AR is the most widely expressed nuclear steroid receptor in all stages of breast cancer, being present in up to 90% of primary mammary tumors and 75% of metastatic tumors." (PMID 37686282, 2023).
breast carcinoma (continued). "A study to determine the clinical significance of AR expression in luminal breast cancer showed that AR-positive cases had better results in terms of time to recurrence (TTR) and disease specific survival (DSS)." (PMID 37099044, 2023). "The initial results from clinical trials indicated a potential clinical benefit for targeting the AR pathway in breast cancer." (PMID 38067367, 2023). "Understanding the complex role of AR in breast cancer subtypes would be critical in predicting the patients who would be benefit from potential targeted AR therapy." (PMID 37099044, 2023). "It is generally acknowledged that AR plays an important role in the physiology and pathology of men; nevertheless, it also counts a great deal in female breast cancer." (PMID 36929229, 2023). "To investigate the impact of AR expression on the outcome of breast cancer treated with neoadjuvant chemotherapy, we analyzed the correlation between AR status and DFS in molecular subtypes of neoadjuvant breast cancer." (PMID 37099044, 2023). "Low expression levels of AR and BAD are associated with decreased overall survival (OS) and relapse-free survival (RFS) in ER+ breast cancer, while their high levels appear to be protective, as Kaplan–Meier survival analyses show." (PMID 37686282, 2023). "Among these, LAR is characterized by the expression of the androgen receptor (AR), and exhibits genomic characteristics that resemble luminal breast cancers, with a still undefined prognosis and clinical behavior." (PMID 37893593, 2023). "The androgen receptor (AR) is the most abundantly expressed steroid hormone receptor in breast cancer." (PMID 36832085, 2023). "Several samples of tamoxifen-resistant breast cancers had a low level of ER expression and a high level of AR expression." (PMID 37237509, 2023). "Together, our data deepen the knowledge of AR actions in breast cancer and further support the possibility of improving the therapeutic options against ER+ breast cancers through the use of androgen-like drugs." (PMID 37686282, 2023). "Being overexpressed in primary and metastatic mammary cancer, the AR emerges as a new biomarker and a promising therapeutic target in breast cancer." (PMID 36980680, 2023). "Given CDK4/6’s potent activity in breast cancer cells, researchers aimed to inhibit this activity in conjunction with AR inhibitors." (PMID 38067367, 2023). "As a member of the steroid receptor in the nuclear receptor superfamily, the androgen receptor (AR) plays a vital role in breast cancer, together with the estrogen receptor (ER) and progesterone receptor (PR)." (PMID 36929229, 2023). "When this occurs in normal melanocytes, one would expect AR serves as a tumor suppressor, as it was found in a subset of breast cancer." (PMID 36833272, 2023). "A recent phase II clinical trial demonstrated that enzalutamide plus trastuzumab was well tolerated in patients with AR+/HER2+ breast cancer who were pretreated with anti-HER2 therapy, and a subset of these patients had durable disease control." (PMID 37345085, 2023). "For example, the activation of PR, AR, and GR leads to the modification of ER-mediated gene expression in ER+ breast cancer." (PMID 36347335, 2023). "The investigation encompassed human breast cancer T47D cells and prostate cancer C4-2B cells, highlighting the pivotal roles of AR, Runx2, and dihydrotestosterone (DHT) in this pathway." (PMID 37759471, 2023). "The synthetic androgen R1881 rapidly stimulates the assembly of the AR/Src complex, leading to distinct cell progression in breast cancer." (PMID 37681860, 2023). "Although several findings support a role for the androgen/AR axis in breast cancer, its involvement in the pathogenesis and progression of this cancer remains under debate." (PMID 36766786, 2023).